PTPN11 (protein tyrosine phosphatase non-receptor type 11)
Diseases named in the same sentence as PTPN11 in open-access papers (continued):
Sharing a sentence is not in itself a finding about the gene and the disease.
pulmonary lymphangiectasis (2 papers, 2022 to 2025). "Patients with PTPN11-mutations showed a slightly higher rate of pulmonary lymphangiectasia during infancy than patients with RIT1-mutations who showed a higher prevalence of peripheral/genital edema." (PMID 35778409, 2022).
retinal degeneration (2 papers, 2013 to 2018). Degeneration of the retina. "Applying genetic ablation of PTPN11 gene in animal studies resulted in extensive retinal degeneration, cell death and optic neuropathy during various developmental stages highlighting its regulatory function in retinal neuroprotection and progenitor retinal cell fate." (PMID 29636665, 2018).
rhabdomyosarcoma (2 papers, 2024). A rare aggressive malignant mesenchymal neoplasm arising from skeletal muscle. "PTPN11 mutations and the RAS pathway may also play a role in the pathogenesis of rhabdomyosarcoma (RMS)." (PMID 39336782, 2024).
Stroke (2 papers, 2021 to 2023). Sudden impairment of blood flow to a part of the brain due to occlusion or rupture of an artery to the brain. "Our study provides evidence supporting the potential causal role of PTPN11 in stroke." (PMID 34859065, 2021). "In addition, the genome-wide significant stroke risk locus rs7974266 was upstream of differentially expressed gene PTPN11, rs12539561 was downstream of differentially expressed gene PIK3CG, and the 3-prime UTR variant rs42035 was downstream of differentially expressed outcome gene CDK6." (PMID 36691064, 2023).
(CMMRD) syndrome (1 paper, 2022).
abdominal aortic aneurysm (1 paper, 2022). Enlargement and ballooning of the vessel that supplies arterial blood to the abdomen, pelvis and legs. "The abdominal aortic aneurysm was diagnosed in a patient with a PTPN11 mutation 2.2 years after GH treatment initiation." (PMID 34939937, 2022).
acral melanoma (1 paper, 2025). "Strikingly, the study of acral melanoma also identified recurrent driver mutations in RTK/RAS signaling genes, including PTPN11, KIT, NF1, KRAS, and NRAS, all of which are recurrent in human AML (and commonly associated with NPM1c mutations)." (PMID 40773291, 2025).
alexithymia (1 paper, 2022). An agnosia that is a deficiency in understanding, processing, or describing emotions. "Alexithymia and internalizing problems were more frequent in patients with variants in PTPN11 and SOS1, while PTPN11 patients also showed higher levels of externalizing problems." (PMID 36012976, 2022). "In the PTPN11 group, significantly more deviant scores than expected were observed regarding FSIQ, alexithymia, and both internalizing and externalizing problems." (PMID 36012976, 2022). "Regarding psychopathology, the findings largely confirmed our hypotheses, insofar as alexithymia was significantly present in two groups, PTPN11 and SOS1, while it was credibly present in PTPN11/NSML, SHOC2, CBL, and SOS2 as well." (PMID 36012976, 2022). "For PTPN11/NSML, SHOC2, CBL, and SOS2, alexithymia was more present than expected." (PMID 36012976, 2022).
aortic atherosclerosis (1 paper, 2014). A atherosclerosis that involves the aorta. "PTPN11 can positively regulate endothelial cell motility and angiogenesis, and increased PTPN11 expression may possibly accelerate aortic atherosclerosis." (PMID 25123136, 2014).
Arrhythmia (1 paper, 2025). Any cardiac rhythm other than the normal sinus rhythm. "There have also been reports of NSML patients exhibiting non-sustained ventricular tachycardia, and it seems that patients without PTPN11 variants do not have an increased risk of arrhythmia." (PMID 39898109, 2025).
atrial fibrillation (1 paper, 2022). A disorder characterized by an electrocardiographic finding of a supraventricular arrhythmia characterized by the replacement of consistent P waves by rapid oscillations or fibrillatory waves that vary in size, shape and timing and are accompanied by an irregular ventricular response. "There was one SAE of atrial fibrillation reported in a 14‐year-old male patient who was PTPN11 negative and RIT1 positive, which has previously been described." (PMID 35245205, 2022).
Azoospermia (1 paper, 2024). Absence of any measurable level of sperm,whereby spermatozoa cannot be observed even after centrifugation of the semen pellet. "Testicular biopsy for immunohistochemical staining was available for Case 1 carrying the PTPN11 p.N308D variant and a control subject with obstructive azoospermia but histologically active spermatogenesis." (PMID 38654924, 2024).
B-cell neoplasm (1 paper, 2025). A group of heterogeneous lymphoid tumors generally expressing one or more B-cell antigens or representing malignant transformations of B-lymphocytes. "Whole-exome sequencing revealed an elevated somatic copy number alteration burden and pathogenic variants in ARID1A, KMT2D, BCL7A, PTPN11, and NUP214, suggesting disruptions in chromatin remodeling, B-cell neoplasm pathogenesis, and oncogenic signaling driving the tumorigenesis." (PMID 41378284, 2025).
bleeding disorders (1 paper, 2021). "The mutational spectrum of patients with bleeding disorders was largely overlapping with that of the NS general population, including mutations in PTPN11, SOS1, RIT1, BRAF, and MAP2K1 genes." (PMID 34857025, 2021).
cardiac anomaly (1 paper, 2022). "In total 55% (n = 11) of the non-PTPN11 group had a cardiac anomaly; of them, 73% (n = 8) were diagnosed with PS, and 25% (n = 2) required intervention of either catheterization (n = 1) or surgery (n = 1)." (PMID 36160796, 2022).
cerebellar hemangioblastoma (1 paper, 2016). A histologically benign tumor, usually cystic with a vascular mural nodule, that is most often found in the cerebellum though it has been reported at other sites within the neuraxis. "Accordingly, we hypothesize that the PTPN11 gene may act in a cell-specific manner: as a tumor suppressor on one hand in the progenitor cells of spinal hemangioblastomas, whilst it acts as an oncogene in the cells of origin of cerebellar hemangioblastoma tumors." (PMID 26768750, 2016).
cerebral astrocytoma (1 paper, 2022). An astrocytoma that arises from the cerebral hemispheres. "We present the first case of a somatic pathogenic variant (T507K) in PTPN11 causing a LO phenotype characterized by severe lateralized overgrowth, vascular proliferation, and cerebral astrocytoma." (PMID 35778969, 2022).
Coffin-Siris syndrome 1 (1 paper, 2022). Any Coffin-Siris syndrome in which the cause of the disease is a mutation in the ARID1B gene. "PTPN11 (Noonan syndrome 1, OMIM 163950) and ARID1B (Coffin-Siris syndrome 1, OMIM 135900) were recurrently reported in 11 patients and 10 patients, respectively." (PMID 35346031, 2022).
congenital cardiomyopathy (1 paper, 2022). "However, it attempted to determine other genotype–phenotype correlations, such as the definitive association of mutations of PTPN11 and the presence of craniofacial anomalies, and the incidence of congenital cardiomyopathy with SOS1 mutations." (PMID 36291422, 2022).
craniosynostosis (1 paper, 2024). Craniosynostosis is defined as the premature fusion of one or more cranial sutures leading to secondary distortion of skull shape resulting in skull deformities with a variable presentation. "Craniosynostosis has been described in individuals with pathogenic variants in other genes of the RAS/MAPK pathway including BRAF, KRAS, PPP1CB, SHOC2, PTPN11, RAF1, and HRAS." (PMID 37774117, 2024).
depression (1 paper, 2023). "The potential target genes Ntn1, Unc5b, Ptpn11, and Src are included in this pathway and participate in the process of psychiatric disorders such as depression." (PMID 37091805, 2023).
diffuse astrocytoma (1 paper, 2017). A low-grade (WHO grade II) astrocytic neoplasm. "Additional somatic alterations included BRAF p.V600E mutation in the pleomorphic xanthoastrocytoma and PTPN11, ATRX, and NF1 mutations in the diffuse astrocytoma." (PMID 28699883, 2017). "In the diffuse astrocytoma, we show that the germline CDKN2A/B deletion was accompanied by somatic loss of the remaining CDKN2A/B alleles as well as an activating hotspot mutation in PTPN11 and inactivating frameshift mutations in the ATRX and NF1 tumor suppressor genes." (PMID 28699883, 2017).
eosinophilic gastroenteritis (1 paper, 2025). "The relationship between eosinophilic gastroenteritis and the PTPN11 gene has not yet been reported." (PMID 40514730, 2025).
exostosis (1 paper, 2014). Non-neoplastic overgrowth of bone. "We also conditionally inactivated Ptpn11 in vivo and examined the effects of SHP2 depletion on chondrocyte maturation and specification, and we examined chondrocyte maturation in exostosis lesions from MC patients." (PMID 24875294, 2014).
fragile X syndrome (1 paper, 2023). A genetic syndrome caused by mutations in the FMR1 gene which is responsible for the expression of the fragile X mental retardation 1 protein. "Fragile X syndrome (FXS) is similarly well characterized by hyperactivated MAPK signaling within neurons, and the causal Fragile X Mental Retardation Protein (FMRP) RNA-binding translational regulator is proposed to directly bind PTPN11/SHP2 mRNA." (PMID 36701299, 2023).
giant cell tumor (1 paper, 2022). A benign, intermediate, or malignant tumor that arises from the bone or soft tissue. "We also recognized 2 patients (6%) with benign, non-cancerous, tumors: both patients had giant-cell tumors (affecting the left tibia and the nerve sheath of the first finger of the right hand, respectively); in the respective cases, PTPN11 and SOS1 mutations were identified." (PMID 36566191, 2022).
haemorrhage (1 paper, 2022). "Orrego-González reported a case of a 12-year-old girl who was an NS patient with PTPN11 mutation complicated by intracerebral haemorrhage, but no specific cause was found." (PMID 35953836, 2022).
hemangioblastoma (1 paper, 2016). "In this study, we have demonstrated in two different tumor cohorts and using two different techniques for copy number alteration detection, SNP and digital PCR, that Chek2 is deleted and EGFR, PTPN11, Ptch1 amplified in majority of hemangioblastoma patients." (PMID 26768750, 2016). "The fact that we find the PTPN11 gene is deleted in some hemangioblastoma patients and is amplified in others may suggest that these tumors actually originate from different cellular lineages." (PMID 26768750, 2016).
Hernia (1 paper, 2020). "Together, our results show that PIK3R1, PTPN11, TGFBR1, CDC42, and SOS1 are probably the most essential proteins involved in human hernia formation." (PMID 31910207, 2020).
hydrops fetalis (1 paper, 2025). Hydrops fetalis is a severe and challenging fetal condition usually defined as the excessive accumulation of fetal fluid within the fetal extravascular compartments and body cavities that manifests as edema, pleural and pericardial effusion and ascites. "A term male infant was diagnosed antenatally with hydrops fetalis due to NS (PTPN11), for which thoracic shunts were placed." (PMID 40835771, 2025).
hypothalamic hamartoma (1 paper, 2023). "We also reported somatic variants of PTPN11 in hypothalamic hamartoma with epileptogenicity originating during fetal development, such as FCD." (PMID 36864519, 2023).
Inguinal hernia (1 paper, 2020). Protrusion of the contents of the abdominal cavity through the inguinal canal. "We discovered that PIK3R1, PTPN11, TGFBR1, CDC42, SOS1, and KRAS were the most essential inguinal hernia-causative proteins and UBC, GRB2, CTNNB1, HSP90AA1, CBL, PLCG1, and CRK were listed as the most commonly-involved downstream proteins." (PMID 31910207, 2020). "Additionally, others also show that inguinal hernia-related essential proteins, PTPN11, CDC42, and SOS1 regulate the RAS/MAPK signaling pathway, which is another downstream effector of RTKs." (PMID 31910207, 2020). "Five essential proteins (PIK3R1, PTPN11, TGFBR1, CDC42, and SOS1) and three downstream common proteins (UBC, GRB2, and CTNNB1) were found to be related to inguinal hernia development." (PMID 31910207, 2020). "Thus, proteins PIK3R1, CDC42, TGFBR1, PTPN11, UBC, CTFR, and SOS1 may play an important role in the inguinal hernia PPI network." (PMID 31910207, 2020).
intestinal tumors (1 paper, 2016). "However, Ptpn11 E76K knock-in mice failed to develop any intestinal tumors after 1 year." (PMID 27582544, 2016).
intrauterine growth restriction (1 paper, 2026). "Our data confirm a mild but consistent intrauterine growth restriction, particularly in children with PTPN11 or SOS1 variants." (PMID 41577878, 2026).
iris coloboma (1 paper, 2018). "In 2 patients with NS due to a PTPN11 mutation, keratoconus is found and the patient with iris coloboma also has a PTPN11 mutation." (PMID 29948256, 2018).
leukoplakia (1 paper, 2025). A white patch or plaque on a mucous membrane that cannot be characterized clinically or pathologically as any other disease. "However, oral submucous fibrosis and leukoplakia had 1 common overexpressed gene (PTPN11) and 1 common underexpressed gene (ST7L)." (PMID 40818124, 2025). "We have identified two common genes, PTPN11 and ST7L, that are commonly deregulated in the precancerous conditions OSF and oral leukoplakia, despite their distinct etiological origins." (PMID 40818124, 2025).
Macrocephaly (1 paper, 2024). Occipitofrontal (head) circumference greater than 97th centile compared to appropriate, age matched, sex-matched normal standards. "In addition, two children in our sample, one with a mutation in PTPN11, and the other with mutations in TSC2 and SRCAP, also exhibited macrocephaly (a structural anomaly)." (PMID 39350038, 2024).
mitral valve prolapse (1 paper, 2025). A fairly common and often benign valvular heart disorder characterized by redundancy or hooding of mitral valve leaflets so that they prolapse into the left atrium, often causing mitral regurgitation. "We more frequently identified ASD (n = 3, 75%) with PTPN11 variants and variable cardiac conditions, including mitral valve prolapse (n = 2, 50%) and tricuspid regurgitation (n = 1, 25%), with RIT1 variants." (PMID 40467618, 2025).
monocytic leukemia (1 paper, 2022). "PTPN11 mutations are frequently associated with acute myelomonocytic/monocytic leukemia subtypes, and PTPN11 is associated with lower rates of complete remission and shorter overall survival." (PMID 36699453, 2022).
multiple sclerosis (1 paper, 2021). A progressive autoimmune disorder affecting the central nervous system resulting in demyelination. "Previous GWASs have implicated PTPN11 in peripheral artery disease, blood pressure, and multiple sclerosis." (PMID 34859065, 2021).
myocarditis (1 paper, 2023). Myocarditis is a condition that is characterized by inflammation of the heart muscle (myocardium). "PTPN11 is involved in tumorigenesis by inducing excessive activation of mitochondrial function; however, its role in myocarditis remains unclear." (PMID 36760573, 2023). "By combining PD-L1-related proteins, we found that mTOR, GSK3β, PTPN11, and MFN2 may be potential diagnosis and treatment biomarkers of ICI-associated myocarditis." (PMID 36760573, 2023). "By analyzing coexpressed proteins, we found four hub proteins that may lead to the occurrence of ICI-related myocarditis, mammalian target of rapamycin (mTOR), GSK3β, PTPN11, and MFN2." (PMID 36760573, 2023). "Second, we confirmed that mTOR, GSK3β, PTPN11 and MFN2 are highly expressed in ICI-related myocarditis by proteomic sequencing, cellular experiments are required to verify our hypothesis." (PMID 36760573, 2023).
periodontitis (1 paper, 2025). An acute or chronic inflammatory process that affects the tissues that surround and support the teeth. "The mother of the patients showed some oral manifestations such as periodontitis and enamel problems; however, poor oral hygiene alone or superimposed with the PTPN11 mutation might have led to these oral features." (PMID 41373572, 2025).
plasma cell neoplasm (1 paper, 2025). A clonal proliferation of immunoglobulin-secreting plasma cells. "These somatic alterations have been implicated in various processes central to plasma cell neoplasms, from chromatin remodeling (ARID1A, KMT2D, and BCL7A) to oncogenic signaling (PTPN11, NUP214)." (PMID 41378284, 2025).
Short stature (1 paper, 2022). A height below that which is expected according to age and gender norms. "In an IGF-I generation test study, 12 pre-pubertal NS children with mutations in PTPN11 did display a blunted increase in IGF-I compared with 12 children with idiopathic short stature; however, the majority of the NS children did not display classic biochemical GH insensitivity." (PMID 35245205, 2022).
Stillbirth (1 paper, 2025). Death of the fetus in utero after at least 22 weeks of gestation. "A study on exome sequencing found that missense mutations of COL2A1, PEIZO1, and HNF1B were associated with stillbirth, and ultra-rare variants in PTPN11, SMC3, and FBN2 were known to cause stillbirth." (PMID 39906474, 2025).
structural epilepsies (1 paper, 2023). "Protein Tyrosine Phosphatase Non-receptor Type 11 (PTPN11) has been recently discovered as a new candidate gene in brain tissue obtained from drug-resistant structural epilepsies." (PMID 36973520, 2023).
T-cell ALL (1 paper, 2022). "Several pairs of co-occurring mutations were found: NRAS with SETD, NRAS with PTPN11 in B-cell ALL (p = 0.024 and p = 0.020, respectively), and NOTCH1 with FBXW7 in T-cell ALL (p < 0.001)." (PMID 36362526, 2022).
Tetralogy of Fallot (1 paper, 2022). A congenital cardiac malformation comprising pulmonary stenosis, overriding aorta, ventricular septum defect, and right ventricular hypertrophy. "In addition, the PTPN11 gene is a candidate gene for contributions to the risk of the nonsyndromic tetralogy of Fallot." (PMID 36496429, 2022).